CPA4 (carboxypeptidase A4)
Diseases named in the same sentence as CPA4 in open-access papers (continued):
Sharing a sentence is not in itself a finding about the gene and the disease.
staphylococcus aureus infection (1 paper, 2024). An infectious process in which the bacteria Staphylococcus aureus is present. "The results showed that CPA4 and staphylococcus aureus infection, protein digestion and absorption and other functions are related." (PMID 38494845, 2024).
cancer (22 papers, 2016 to 2025). A tumor composed of atypical neoplastic, often pleomorphic cells that invade other tissues. "Although it has been two decades since CPA4’s discovery and its association with cancer development and progression, it is still a very nascent research topic." (PMID 40805261, 2025). "Previous studies have demonstrated that CPA4 is closely associated with the aggressiveness, growth, and differentiation in cancer cells." (PMID 34827136, 2021). "Many studies have shown that CPA4 is a significant biomarker of poor prognosis in lots of cancers and is associated with the upregulation of CPA4 with poor overall survival." (PMID 34827136, 2021). "Various studies have shown that CPA4 is closely associated with the growth, differentiation, and aggressiveness of cancer cells." (PMID 30875843, 2019). "As a secreted proteinase, CPA4 was closely associated with the establishment of cancer microenvironment to facilitate cancer progression." (PMID 27780921, 2016). "This association suggests that CPA4 may influence cancer stem cell maintenance and progression through modulation of GPCR pathways." (PMID 40805261, 2025). "In this review, we provide a brief description of peptidases, their classification, history of CPA4, mechanism of action of CPA4 as a peptidase, its expression in various tissues, including cancers, its role in various tumor types, the associated molecular pathways and cellular processes." (PMID 40805261, 2025). "The aberrant expression of CPA4 is associated with cancer progression." (PMID 31424161, 2019). "Some studies have proposed the activation of the PI3K pathway as a possible mechanism for CPA4 activity in cancer cells, while others propose activation of STAT and ERK pathways." (PMID 40805261, 2025). "CPA4’s role in cancer has been attributed to its disruption of many cellular signaling pathways, e.g., PI3K-AKT-mTOR, STAT3-ERK, AKT-cMyc, GPCR, and estrogen signaling." (PMID 40805261, 2025). "In conclusion, CPA4 represents a compelling link between proteolytic regulation and cancer pathogenesis." (PMID 40805261, 2025). "The role of CPA4 in cancer development, treatment response and drug resistance has been explored over many years." (PMID 40805261, 2025). "Carboxypeptidase A4 (CPA4) has been identified as a regulator of cancer progression and serves as a reliable biomarker in various tumors." (PMID 40740483, 2025). "Carboxypeptidase A4 (CPA4) is a zinc‐containing metallocarboxypeptidase with implications in various cancer types, but its role in ccRCC remains unexplored." (PMID 38494845, 2024). "In paired pan‐cancer samples, the expression of CPA4 is increased in various malignancies, including KIRC." (PMID 38494845, 2024). "We obtained mRNA expression profile of CPA4 in pan‐cancer and corresponding normal tissues via the TCGA and the GTEx database." (PMID 38494845, 2024). "Cancer tissues of ccRCC presented higher IHC staining scores of CPA4 than paracancerous tissues (p < 0.05)." (PMID 38494845, 2024). "The Cancer Genome Atlas (TCGA) and Gene Expression Omnibus (GEO) databases were utilized in order to investigate the differential expression patterns of CPA4." (PMID 38494845, 2024). "Previous research has shown a link between CPA4 overexpression and the growth, metastasis and invasion of several cancers." (PMID 38494845, 2024). "CPA4 has also been reported to promote stemness and epithelial mesenchymal transition in different types of cancers." (PMID 37162264, 2023). "Carboxypeptidase A4 (CPA4) is a member of the metallo carboxypeptidase family which have been identified to be involved in cancer biology and insulin sensitivity." (PMID 36824368, 2023). "CPA4 is a novel biomarker for cancer that is prevalent in a variety of cancers and is recognized to regulate inflammation, playing an essential role in the tumor microenvironment as well as tumor cell proliferation and invasion." (PMID 37162264, 2023).
cancer (continued). "Promoter methylation of CPA4 in the TCGA-BLCA data was significantly lower than that of normal tissues adjacent to cancer in the UALCAN webpage (p < 0.001)." (PMID 34827136, 2021). "Carboxypeptidase A4 (CPA4) has shown the potential to be a biomarker in the early diagnosis of certain cancers." (PMID 34827136, 2021). "In recent years, CPA4 has shown the potential to be a biomarker in the early diagnosis with clinical benefit for certain cancers." (PMID 34827136, 2021). "The results indicated that suppression of CPA4 in LTT cells significantly suppressed cancer cell growth." (PMID 33746592, 2021). "Recently, CPA4 has shown the potential to be a biomarker in the early diagnosis for certain cancers." (PMID 34827136, 2021). "CPA4 was first discovered when screening for upregulated mRNA during cancer cell differentiation induced by sodium butyrate." (PMID 34827136, 2021). "CPA4 is one of the members of the metallocarboxypeptidase family and it participates in cancer biology." (PMID 32347291, 2020). "For example, the down-regulation of CPA4 represses cancer growth by inhibiting the c‐MYC pathway in human non-small cell lung cancer." (PMID 32347291, 2020). "Accordingly, it is arguable that adequate prognostication by serum CPA4 levels depends on the specific type of cancer in question." (PMID 30875843, 2019). "It has been suggested that the presence of high CPA4 expression can be used as a precise marker of metastasis in certain cancers." (PMID 30875843, 2019). "Recent research focused on prolonged survival has suggested that carboxypeptidase A4 (CPA4) plays a role in both tumor microenvironment formation and distant metastasis in cancer." (PMID 30875843, 2019). "Carboxypeptidase A4 (CPA4) is a member of the metallocarboxypeptidase family, and is aberrantly overexpressed in some types of cancer tissues." (PMID 27780921, 2016). "However, subsequent studies have reported the overexpression of CPA4 in different types of cancer but have done little to explain how it is consistently elevated in these tumors." (PMID 40805261, 2025). "We further discuss the limitations of current literature linking CPA4 to cancers and challenges that prevent using CPA4 as a biomarker for cancer aggressiveness and predicting drug response and highlight a number of future strategies that can help to overcome the limitations." (PMID 40805261, 2025). "CPA4 is a signaling molecule that plays a pivotal role in various cellular processes, including cell growth, differentiation, apoptosis and serves as a tumor promoter leading to cancer aggressiveness and drug resistance." (PMID 40805261, 2025). "The hypoxic changes in the tumor microenvironment may be responsible for the frequent overexpression of CPA4 commonly seen in different cancers." (PMID 40805261, 2025). "The Wilcoxon rank sum test was used to evaluate the differential expression of CPA4 in pan‐cancer." (PMID 38494845, 2024). "In addition, GFPT2 and SRPX2, which are closely related to CPA4, also promote the progression of various cancers." (PMID 38494845, 2024). "The high expression of CPA4 in various cancer tissues suggests that CPA4 could be used as a potential target for the clinical treatment of tumours." (PMID 38049405, 2023). "However, one trial showed that CPA4 is a protective factor in muscle-invasive bladder cancer, contrary to the role of CPA4 in most cancers." (PMID 34827136, 2021). "CPA4, a member of the metallo-carboxypeptidase family, is overexpressed in a variety of cancers." (PMID 34049287, 2021). "The expression of CPA4 in pan-cancer was analyzed between tumor and normal tissues." (PMID 34827136, 2021). "All of these results suggest that CPA4 could be regarded as an emerging target or promising biomarker for cancer therapy." (PMID 34827136, 2021). "The roles of CPA4 in cancer biology have been widely investigated." (PMID 32347291, 2020). "A previous report showed that CPA4 activated STAT3 in cancer cells." (PMID 32347291, 2020).
cancer (continued). "Current studies have identified the roles of CPA4 in cancer biology and insulin sensitivity." (PMID 32347291, 2020). "It was also reported that the high levels of CPA4 could be utilized as a biomarker of metastasis in certain cancers when assessed together with lymph-node involvement." (PMID 30875843, 2019). "There have been several studies indicating that CPA4 might be of clinical benefit in the early diagnosis of certain cancers." (PMID 30875843, 2019). "Taken together, these observations indicated that CPA4 might play a key role in the cancer metastasis." (PMID 27780921, 2016). "Aberrant expression of CPA4 was found in some types of cancer tissues, and it could be measured as cancer markers for early detection." (PMID 27780921, 2016). "Targeting CPA4 could serve as a novel strategy to reduce cancer burden and improve drug response." (PMID 40805261, 2025). "As research continues, CPA4 could emerge as a novel tool in the diagnosis and treatment of various malignancies, potentially contributing to more personalized, safe and effective cancer care." (PMID 40805261, 2025). "For one thing, CPA4 could degrade extracellular matrix and facilitate cancer cell invasion." (PMID 27780921, 2016). "STAT3 and ERK signaling: CPA4 is known to promote tumor progression through activation of the STAT3 and ERK signaling pathways in various cancers." (PMID 40805261, 2025). "Other notable proteins, such as ACKR3, COL11A1, CPA4, and FZD6, were previously reported as potential therapeutic targets in cancer." (PMID 38652547, 2024). "It has been suggested that CPA4, an important regulator of inflammation, also plays a role in tumor microenvironment (TME) formation and distant metastasis in cancer." (PMID 30875843, 2019). "Although CPA4 has been found to regulate cancer aggressiveness and poor prognosis, no comprehensive review summarizing the role of CPA4 in cancer is available so far." (PMID 40805261, 2025). "Our results may provide new insight into the mechanism by which ANG1 enhances the development of cancer and indicate that the ANG1/CPA4 axis has the potential to be a novel target for TNBC treatment." (PMID 37162264, 2023). "Although CPA4 expression has been confirmed to have potential significance in multiple types of cancer, no studies have shown the expression level and clinical significance of CPA4 in BLCA." (PMID 34827136, 2021).
tumor (19 papers, 2016 to 2025). "The survival findings of DSS (HR = 2.57, p < 0.001) and PFI (HR = 1.80, p < 0.001) show that tumour patients with high CPA4 expression were at risk." (PMID 38494845, 2024). "It has been implicated that CPA4 leads to a poor prognosis by regulating tumor proliferation and the expression of stem cell characteristics, and can be used as a potential therapeutic target for HCC patients." (PMID 34049287, 2021). "The immune infiltration in the tumor microenvironment has also been shown to be associated with CPA4." (PMID 34827136, 2021). "Subsequently, more studies conducted found marked increases in the CPA4 levels in patient tissue and serum samples and associated these findings with tumor progression and poor prognosis." (PMID 30875843, 2019). "This association implies that CPA4 may influence tumor progression through interactions with hormone-dependent cellular processes, including those mediated by estrogen receptors." (PMID 40805261, 2025). "If truly CPA4 plays a role in tumor aggressiveness and drug resistance, future studies must explore new ways to inhibit CPA4 and assess the effect of inhibition on tumor prognosis." (PMID 40805261, 2025). "More importantly, tumor tissues have significantly high CPA4 expression compared to normal tissues (p < 0.05)." (PMID 40805261, 2025). "For example, CircCHST15 inhibits the expression of PD-L1 in tumor cells, and the up-regulation of circ-CPA4 enables tumor cells to deliver PD-L1 to tumor microenvironment through exosomes." (PMID 40296917, 2025). "There is significant evidence from the literature that CPA4 promotes tumor progression by regulating cell proliferation and survival, EMT, invasion and metastasis." (PMID 40805261, 2025). "It has been found that circ-CPA4 can down-regulate let-7miRNA, which promotes tumor cells to secrete exosomal PD-L1 into the TME." (PMID 40296917, 2025). "Significant differences in immune infiltration scores were observed between high and low CPA4 expression groups across various immune cell types, indicating a strong correlation between CPA4 expression and the tumor’s immune activation state." (PMID 40805261, 2025). "The shift from Th1 to Th2 dominance accelerates the immunosuppressive response in the tumour microenvironment, which was consistent with the positive correlation between CPA4 expression and Th2 cell infiltration." (PMID 38494845, 2024). "Strong associations were seen between the expression of CPA4 and the TNM stage, pathological stage and histological grade of the tumour." (PMID 38494845, 2024). "In both paired samples and unpaired samples of the TCGA‐KIRC database, the level of CPA4 expression in tumour tissues was found to be significantly greater compared to normal tissues (p < 0.05)." (PMID 38494845, 2024). "Protein samples from tumor tissues showed that CPA4 level was also increased in the ANG1 overexpression group in comparison with the control group." (PMID 37162264, 2023). "CPA4 acts as a pro-oncogenic element in various tumors and is capable of promoting tumor progression, EMT, metastasis and stemness." (PMID 37162264, 2023). "Recent research suggested that CPA4 plays an important role during the process of tumor microenvironment formation and distant metastasis." (PMID 35686102, 2022). "We analyzed the DEGs in altered expressions of CPA4 including in low and high samples to explore the potential mechanisms of CPA4 that promote tumor progression." (PMID 34827136, 2021). "In accordance with our above results, Western blot analysis revealed that p‐AKT and c‐MYC expression was decreased in the CPA4 knockdown tumor tissues compared with shCtrl tumor tissues." (PMID 31397502, 2019). "It is thought that CPA4, one of these markers common to different tumor types, is effective in the TME formation during oncogenesis." (PMID 30875843, 2019). "The results showed that CPA4 was increased in 93 of the 131 (71%) tumor tissues compared with that in the adjacent tissues." (PMID 31397502, 2019).
tumor (continued). "For another, CPA4 was highly stained around micro-vessels area, and it is possible to contribute to tumor angiogenesis." (PMID 27780921, 2016). "In ccRCC, CPA4 was found to influence immune cell infiltration, suggesting its potential role in regulating tumor immune microenvironment (TIME), which might impact immunotherapy response." (PMID 40805261, 2025). "CPA4 is a downstream target of let-7, which is a known tumor suppressor." (PMID 40805261, 2025). "Furthermore, CPA4 overexpression in PC tissues was positively related with tumor size (p = 0.026), T stage (p = 0.011), lymph node metastasis (p = 0.026) and worse prognosis (p = 0.001)." (PMID 40805261, 2025). "GSEA results indicated that CPA4 was closely related to epithelial–mesenchymal transition (EMT), oxidative phosphorylation (OXPHOS) and other epigenetic genes which demonstrate a close association with tumour cells." (PMID 38494845, 2024). "Additionally, immune infiltration analysis suggested a potential link between CPA4 expression and immune response in the tumour microenvironment." (PMID 38494845, 2024). "Compared with the control group, the silencing CPA4 group could promote the killing effect of HGS-ETR1 on tumours in mice, and the tumour volume and weight were smaller than those of the control group." (PMID 38049405, 2023). "The detection of GSDME protein in mouse tumour by western blot also found that the group with overexpression of CPA4 could inhibit the occurrence of pyroptosis in tumor tissues compared with the control group." (PMID 38049405, 2023). "From the cellular and biochemical characteristics, CPA4 is secreted from cells in the form of soluble proenzyme (pro-CPA4), which might play a role in creating a tumor microenvironment." (PMID 34827136, 2021). "The expression of CPA4 in tumor and normal tissues was compared using the TCGA + GETx database." (PMID 34827136, 2021). "There are a variety of techniques to assess the CPA4 expression in a tumor." (PMID 30875843, 2019). "We found that CPA4 mRNA was significantly upregulated in 14 tumor tissues." (PMID 31397502, 2019). "The result showed that CPA4 knockdown inhibited tumor growth in nude mice." (PMID 31397502, 2019). "TUNEL assay results showed a higher level of cell apoptosis in CPA4 knockdown tumor tissues." (PMID 31397502, 2019). "Furthermore, inhibition of CPA4 expressions in cell lines inhibited tumor growth and spread." (PMID 40805261, 2025). "CPA4 catalyses the release of carboxy‐terminal amino acids, which may be associated with the formation of the tumour microenvironment." (PMID 38494845, 2024). "Finally, in the sub-networks related to target lncRNAs, the expression levels of SOX4, SRM, and CPA4 (with the highest level of expression change based on bioinformatics analysis) mRNAs, in 32 tumor and 32 normal colorectal tissues, were investigated using qRT-PCR." (PMID 39028420, 2024). "Knockdown of circ-CPA4 reactivates CD8+ T cells, suggesting that circ-CPA4 plays a crucial role in modulating the tumor immune microenvironment and resistance to immunotherapy." (PMID 40739089, 2025). "Conversely, overexpression of CPA4 enhances AKT activation and c-MYC levels, promoting cell proliferation and tumor growth in vivo." (PMID 40805261, 2025). "Knockdown of CPA4 led to decreased phosphorylation of STAT3 and ERK, resulting in suppressed tumor growth and metastasis." (PMID 40805261, 2025). "Among the genes negatively regulated by KDM4B, STARD7, CPA4, FKBP14, and RNF6 have been shown to regulate cell proliferation and/or metastasis, whereas DYRK2 is a known tumor suppressor." (PMID 34766154, 2021). "Mechanistically, CPA4 activates the STAT3 and ERK pathways, contributing to tumor progression." (PMID 40805261, 2025). "The dysregulation of these pathways by CPA4 could be responsible for inducing epithelial--mesenchymal transition (EMT), tumor invasion and drug resistance." (PMID 40805261, 2025).